IGF1R (insulin like growth factor 1 receptor)
Diseases named in the same sentence as IGF1R in open-access papers (continued):
Sharing a sentence is not in itself a finding about the gene and the disease.
tumor (continued). "At least one SNP in IGF1R (rs12423791) and three SNPs in IGF1 (rs2162679, rs5742612, rs35767) were associated with tumor response to chemotherapy." (PMID 27144430, 2016). "IGF-1R overexpression has been correlated with tumor aggressiveness while disruption of IGF-1R activation inhibited growth and motility of a wide range of cancers." (PMID 27127884, 2016). "Tumor cells were FACS characterized upon sacrifice to determine IGF1R effect on the plasticity of this cell’s phenotype." (PMID 27179633, 2016). "Collectively, these results reveal activated stromal cells can return a differential signal to tumor cells via an IGF1R/AXL-AKT axis." (PMID 27087446, 2016). "Reciprocal signaling regulates tumor cell proliferation and apoptosis and increases mitochondrial capacity via an IGF1R/AXL-AKT axis." (PMID 27087446, 2016). "To identify potential mediators of sensitivity or resistance to IGF-1R inhibition, we carried out a functional screen with a customised siRNA library that was selected to target 178 oncogenes or tumour suppressors." (PMID 27472395, 2016). "To further study the difference in IGF1R expression between primary tumours and cell lines, we stained the primary tumours corresponding to the cell lines L835, CH2879, L3252B and L2975." (PMID 27418340, 2016). "Before continuing anti-IGF1R therapies, it is necessary to define additional IGF1R-based biomarkers to more accurately predict anti-tumor response and identify responsive tumors." (PMID 25964777, 2015). "In the correlative analysis between IGF-1R expression and clinical parameters, IGF-1R expression was significantly associated with tumor size, N status, stage, and Ki-67." (PMID 26287334, 2015). "In our study, we tested metformin’s anti-tumor effects and we are the first group who attempts to combine metformin with an IGF-1R mAb and confirm their additive effects to target SCLC cells." (PMID 26287334, 2015). "Further, blockade of the IGF1R with antibody can promote IGF1 signaling through the integrin β3 receptor in tumor cells." (PMID 25699021, 2015). "The circulating IGF-1 levels are closely associated with the risk of cancer, and the blockade of IGF-1R, using anti-IGF-R1 antibodies, IGF1R antisense, and inhibitory analogues of IGF-1 suppress tumor cell growth and angiogenesis." (PMID 25638159, 2015). "As a more efficacious alternative, we propose that IGFBPs can be developed as IGF-antagonist based cancer therapeutics serving to block the IGF-1R mediated tumour progression." (PMID 25866791, 2015). "We also evaluated the anti-tumor effects of anti-IGF-1R monoclonal antibody Figitumumab (CP) on SCLC, and tried two drug combinations to improve CP therapy." (PMID 26287334, 2015). "miR-143 and miR-145 are two miRNAs shown to have anti-tumor effects in CRC through their downregulation of insulin-like growth factor 1 receptor (IGF1R)." (PMID 26602923, 2015). "Targeting IGF-1R/IR (insulin receptor) signaling with BMS-754807 has also resulted in cell growth inhibition in several pediatric tumor types, in vitro and in vivo." (PMID 25748921, 2015). "Since, IGFBPs have a sequestration affect that limits bioavailability of circulating IGFs and competitively inhibits IGFs to bind with IGF-1R at pericellular region, leading to the tumor suppressor action of IGFBPs." (PMID 26217584, 2015). "High membranous IGF-1R expression at diagnosis correlated significantly with ER positivity, low tumor stage (stage I/II) and longer overall survival (p < 0.05)." (PMID 25680198, 2015). "In the remainder of this review, we focus on the possible mechanisms for and implications of our data on the function of the IGF-1R in the MMTV-Wnt1 tumor model and in TNBCs." (PMID 26106366, 2015). "To evaluate the relationship between IR and IGF1R levels and tumor latency, we separated the entire group of tumors into five equal clusters each representing 20% of the tumors based on right-angled distribution on the linear regression curve." (PMID 25848982, 2015).
tumor (continued). "New studies in patients with RAS mutated tumours employ MEK inhibitors with either ERBB inhibitors or IGF1R inhibitors, and in patients with BRAF mutated tumours employ BRAF/MEK inhibitors." (PMID 25624878, 2015). "Biased agonism and the binding of IGF1 to the integrin β3 receptor are novel mechanisms of tumor resistance to anti-IGF1R antibodies that we will discuss below." (PMID 25699021, 2015). "Since membranous IGF-1R expression strongly correlated with ER expression and tumor stage, multivariate Cox regression analysis was performed to correct for these variables." (PMID 25680198, 2015). "The combination of HER-1-418 and IGF-1R-56 peptide mimics on TNBC cells (MDA-MB-231) in vitro demonstrated superior anti-tumor efficacy over single treatment." (PMID 26350593, 2015). "The studies reported herein suggest that IGF-1R-targeted approaches create a milieu that stimulates tumour angiogenesis, thus accelerating cancer metastasis and promoting a tumour's adaptive–evasive response to the therapy." (PMID 26465273, 2015). "Interruption of IGF-1R signaling has been shown to inhibit tumor growth and block metastasis formation in a wide variety of tumor models." (PMID 26322273, 2015). "Co-targeting IGF-1R and Src significantly suppressed the proliferation and tumor growth of both high-pSrc-expressing and low-pSrc-expressing NSCLC cells in vitro and in vivo and the growth of patient-derived tissues in vivo." (PMID 26041671, 2015). "Small GTPase RhoA and IGF1R have long been recognized to play an important role in tumorigenesis and tumor progression." (PMID 26151573, 2015). "The IGF-1R signaling pathway plays a critical role in the proliferation and survival of various tumor types." (PMID 26515601, 2015). "Elevated IGF1R expression and signaling in these basal-like tumors appear to have active roles in tumor promotion." (PMID 25964777, 2015). "GSK1904529A is a small molecule inhibitor of IGF-1R and has been demonstrated to inhibit the proliferation of several tumor cells by inhibiting receptor phosphorylation and downstream signaling." (PMID 26035416, 2015). "Consistent with its ERα-dependent regulation, IGF1R levels are reduced in many tamoxifen- and aromatase inhibitor-resistant cell and mouse tumor models as well as patient tumors." (PMID 25964777, 2015). "Previously, we have reported that inhibition of these two pathways using panitumumab (anti-EGFR antibody) and ganitumab (anti IGF-1R antibody) enhanced the FaDu tumor response to radiation." (PMID 25355701, 2015). "The authors of this study further suggested that part of the mechanism for IGFBP-5 in reducing tumor volume after acute treatment with the Wnt pathway inhibitor was due to down-regulation of IGF-1R signaling." (PMID 26106366, 2015). "In an attempt, to combine these different therapeutic strategies in a single formulation we developed recently anti-IGF1R-Dox loaded immunoliposomes and revealed enhanced targeting efficiencies against tumor cell lines of different human origin." (PMID 26497207, 2015). "The administration of 3 infusions IGF1R CAR T cells derived from patient 1 also significantly inhibited tumor growth compared to untreated group at days 6, 14 and 21 post T-cell infusions (p < 0.001)." (PMID 26173023, 2015). "Animal models further propelled this wave, wherein mice and rat models given antisense IGF-1R strategies considerably decreased or abolished in vivo tumor growth yet had very little overall toxicity." (PMID 25964779, 2015). "Although additional validation studies using corroborated clinical samples from IGF-1R-targeted therapies must be performed, our current study reveals malignant progression of tumours in the face of an IGF-1R blockade through IGF-2 secretion in the TME." (PMID 26465273, 2015). "To confirm the interactions between EP2/EP4 and IGF-1R signaling in vivo, we established an orthotopic xenograft model where IGF-1R signaling stimulated tumor growth." (PMID 25638159, 2015).
tumor (continued). "After correction for tumor stage, patients whose tumors showed an increase in IGF-1R expression still had a poorer prognosis compared to patients with tumors showing a decrease in IGF-1R expression." (PMID 25680198, 2015). "As one of the potential targets of BMS-754807 is IGF-1R, we performed a western blot on whole tumor lysates from our mouse model and observed only a slight increase in the levels of phosphorylated IGF-1R in all tumors tested as compared to normal brainstem." (PMID 25748921, 2015). "Inhibition of EGFR and IGF-1R pathways using their respective therapeutic antibodies presented promising results in controlling tumor growth in several preclinical models 24,25." (PMID 25355701, 2015). "Although IGFBPs can prevent IGF from binding to IGF-1R, because of their higher affinity to IGF than the IGF-1R, it can also induce tumour growth and progression in situations where the IGFBP proteases levels are high and/or when IGFBPs interact with ECM." (PMID 25866791, 2015). "In conclusion, 99mTc-ZIGF1R:4551-GGGC can visualize the IGF-1R expression in human tumor xenografts and provides low retention of radioactivity in kidneys." (PMID 25425114, 2015). "OSI-906 is a small molecule IGF1R/IR kinase inhibitor that suppresses the growth of tumor xenografts in mice." (PMID 25699021, 2015). "Common alterations include overexpression of IR and IGF-1R by the malignant cells, increased IR/IGF-1R hybrid formation, deregulated autocrine secretion of IGFs, and increased IGFs secretion by the tumor stroma." (PMID 25798130, 2015). "For example, miR-133a is downregulated in GC and functions as a tumor suppressor in vitro and in vivo partly by repressing IGF1R." (PMID 26576674, 2015). "Cixutumumab is an anti-IGF-1R monoclonal antibody and is used to treat cancer; however, tumours can develop resistance to the therapy." (PMID 26465273, 2015). "In this scenario, it is most likely, that IR-A functions as the main IGF-2 receptor, as the IGF-1R is often saturated by the high levels of IGF-1 of tumor microenvironment." (PMID 25798130, 2015). "Increased Src activation has been reported to confer resistance to anti-IGF-1R therapeutics in various tumor cells." (PMID 26515601, 2015). "The tumor-to-blood ratios were also higher than the ones previously reported for anti-IGF-1R antibody R1507 (2.8 ± 0.7) at 72 h after injection." (PMID 25425114, 2015). "Considering the roles of IGF/IGF1R in transformation, tumor growth, and resistance to cell death, anti-IGF1R antibodies were designed for cancer therapy." (PMID 25699021, 2015). "Together, these findings suggest that IGF-1R blockade can promote communication between cancer and stromal cells, thereby promoting tumour angiogenesis." (PMID 26465273, 2015). "Their target prediction and pathway analysis showed that miR-126 can regulate key molecules and critical pathways involved in ccRCC tumor development and progression, including the IGF1R, BCL2, HIF-1, VEGF, mTOR, and PI3K-Akt signaling pathways." (PMID 26416448, 2015). "Elevated expression of IGF1R was previously reported in tumor samples of patients with ER-negative breast cancers." (PMID 25749031, 2015). "Because the effects of metformin and CP were quite similar in terms of receptor down-regulation and IGF-1R signaling pathway inhibition, we then asked if there are any additive anti-tumor effects when combining metformin with CP." (PMID 26287334, 2015). "This study demonstrated that Syndecan-1 liposomes were able to release cargo into IGF1-R expressing tumor cells." (PMID 26627455, 2015). "The results of different studies indicate that tumor proliferation and survival is dependent on the IGF1R and IR, and that their inhibition leads to reductions in proliferation and increases in cell death." (PMID 25699021, 2015).
tumor (continued). "Despite promising data in preclinical models and a strong rationale for targeting the IGF signaling pathway in cancer, clinical efficacy of select IGF-1R inhibitors has been disappointing in multiple studies across many different tumor types." (PMID 26317790, 2015). "In fact, a compensatory activation of insulin receptor-AKT signaling has been previously reported with IGF-1R monoclonal antibody therapy in human tumor cells." (PMID 26317790, 2015). "The same team has previously reported that doxycycline-induced downregulation of IGF-1R in mammary epithelium using the same animal model induced tumor regression." (PMID 25743390, 2015). "Specifically, we postulate that novel combination treatments targeting members of the EGFR family and IGF-1R will yield significant anti-tumor effects in in vitro models of EC and TNBC possibly overcoming mechanisms of resistance." (PMID 26350593, 2015). "In further experiments, a human CRC cell line overexpressing the IGF-1R – HCT116/IGF-1R – resulted in highly invasive tumor and produced distant metastases in murine models, whereas the parental cell line did not." (PMID 26528439, 2015). "Several clinical and experimental studies have reported that increased circulating IGF-1 levels and increased expression of IGF-1 and IGF-1R in tumor tissues are involved in the development of these malignant tumors." (PMID 25329702, 2014). "In the group that received IGF-1r siRNA treatment alone, the tumor volume was also reduced (2.8 ± 0.1 cm3 for Eca-109 cells; 3.1 ± 0.1 cm3 for TE-1 cells) (P <0.05, n =8)." (PMID 25363593, 2014). "IGF1R is a validated tumor target for developing small molecule inhibitors and antibody therapies that block its tyrosine kinase activity." (PMID 25092925, 2014). "Mitogenic signaling by INSR has been described in some tumor models and examples have been provided in which the IGF1R or INSR compensates for the inhibition of the opposite receptor." (PMID 24434591, 2014). "In vitro and in vivo tumor models have also demonstrated direct interactions between IGF-1R, EGFR/HER-2, and co-localization of IGF-1R and HER-2." (PMID 25424625, 2014). "Although there are two receptors for IGFs, IGF-1R and IGF-2R, IGF-2R does not transduce a signal and acts to reduce the bioavailability of IGF-2 by sequestering it away from IGF-1R and thus acts as a tumor suppressor." (PMID 24885964, 2014). "IGF1R has become a crucial receptor protein in understanding tumor metastasis, and, hence, a therapeutic target." (PMID 25287248, 2014). "miR-99a expressing OEC-M1 cells showed decreased migration and invasion activities and these effects were rescued by ectopic expression of IGF-1R indicating that miR-99a has a role as a tumor suppressor in OSCC via IGF-1R regulation." (PMID 25628647, 2014). "Increased IGF-1R and pAKT levels in a post-relapse human tumor sample were consistent with the proposed role for IGF-1R/PI3K-dependent resistance to BRAF inhibitors." (PMID 24743024, 2014). "M1 demonstrated the greatest response to therapies SCH 717454 and BMS 754807, with near complete regression of tumors in response to antibody SCH 717454 (mean tumor volume in anti-IGF1R antibody arm vs placebo arm at 5 weeks, 1.09 cm3 vs. 0.04 cm3, p<0.001)." (PMID 25170759, 2014). "miR-503 expression is repressed in GBM and its upregulation inhibits IGF-1R expression, suggesting that miR-503 is a candidate tumor suppressor, as well." (PMID 24709958, 2014). "miR-375 can significantly inhibit LSCC cell proliferation, migration, and invasion and promote apoptosis to suppress tumor via IGF1R-mediated AKT signaling pathway." (PMID 25184138, 2014). "It has been well documented that down-regulation of IGF-1R or insulin receptor inhibits cell proliferation, metastasis and in vivo tumor growth." (PMID 24970814, 2014).
tumor (continued). "Our finding is consistent with the previous studies, showing that IGF-1R and/or IR knockdown inhibits the tumor growth as well as increases the chemo-sensitivity." (PMID 24970814, 2014). "Collectively, these data indicated that the targeted degradation of IGF-1R/IR by Ad-PTB-U-box significantly inhibit the in vivo tumor growth of IGF-1R/IR-overexpressing cancer cells, implying its potential as a therapeutic agent." (PMID 24970814, 2014). "Robatumumab has been shown to inhibit tumor growth in various human tumor xenograft models, to induce IGF-1R degradation, and to induce killing of tumor cells through the mechanism of antibody-dependent cellular cytotoxicity 19,20." (PMID 24905030, 2014). "Insulin-like growth factor 1 receptor signaling pathways influence cancer cell proliferation, adhesion, migration, and cell death, and are critical in tumor cell survival and metastasis." (PMID 24410957, 2014). "The involvement of the IGF-1R/ mTOR pathway in tumor initiation and progression is supported by mounting experimental evidence." (PMID 25026290, 2014). "IGF-IR plays a multifunctional role in human CRC growth and is widely regarded as an attractive target for anticancer drug treatment based on the observation that inhibition of IGF-1R function results in apoptosis and inhibition of tumor growth." (PMID 24173770, 2014). "OSI-906 displays in vitro antiproliferative effects in several human tumour cell lines and robust in vivo anti-tumour effects in IGF1R-dependent mice xenograft model of fibrosarcoma." (PMID 25225571, 2014). "The advantage of co-targeting IR and IGF-1R also lies in simultaneous attenuation of cancer growth and cancer metabolism, which can strengthen the anti-tumor efficacy." (PMID 24970814, 2014). "Tumor locations and TNM stage were associated with plasma IGF-1R levels (P = 0.013, P = 0.01, respectively." (PMID 24667580, 2014). "Due to tumor heterogeneity, however, our results indicated a reciprocal regulation that mutually regulates the levels of miR-99a and IGF1R in a part of OSCC cells." (PMID 24410957, 2014). "They found that miR-16 targeted IGF-1R 3′UTR directly suggesting that miR-16 functions as tumor suppressor in OS by targeting IGF-1R and regulating cell proliferation." (PMID 25628647, 2014). "In summary, there are previous studies suggesting that high expression of IGF1R is indicative of a well differentiated tumor with weak metastatic capacity." (PMID 25362932, 2014). "The treatment of blocking IGF-1R with antibodies markedly decreased IGF-1R phosphorylation and downstream activation of Akt and Erk1/2, hereby inhibiting tumor growth." (PMID 25333772, 2014). "Additional studies have demonstrated intensified insulin signaling when IGF1R is interrupted in tumor cells." (PMID 24434591, 2014). "Apart from promoting tumor growth, IGF1R and INSR overexpression also enhanced angiogenesis indicated by higher vessel density and increased number of desmin-immunoreactive pericytes." (PMID 24809298, 2014). "High expression of IGF-1R in human PDAC tissues has also been reported and associates with higher tumor grade and poor survival." (PMID 24667580, 2014). "The tumor locations and TNM stage were associated with plasma IGF-1R levels (P = 0.013 and P = 0.01, respectively)." (PMID 24667580, 2014). "Other studies have also found that IGF1R correlates with “good” prognostic factors such as high ER expression and it has been suggested that IGF1R expression, in accordance with ER, reflects a well differentiated tumor." (PMID 25362932, 2014). "The combined treatment using mTOR inhibitors and IGF-1R antibody/inhibitor has been proved to enhance the anti-tumor effect of mTOR inhibitors." (PMID 25026290, 2014). "In IGF-2- and IGF-1R-positive tumor cells, IGF-1R-specific repressor significantly reduced cell proliferation." (PMID 25289085, 2014). "It has also been shown that OSI-906 provides superior anti-tumor efficacy compared with targeting anti-IGF-1R antibody alone." (PMID 24970814, 2014).